RIPK1 (receptor interacting serine/threonine kinase 1)
Diseases named in the same sentence as RIPK1 in open-access papers (continued):
Sharing a sentence is not in itself a finding about the gene and the disease.
psoriasis (continued). "Among these drugs, pharmacological inhibitors of the receptor-interacting serine/threonine protein kinase 1 (RIPK1) have entered clinical trials for the treatment of autoimmune diseases (psoriasis, ulcerative colitis and rheumatoid arthritis), as well as some cancers and neurological disorders." (PMID 37090247, 2023). "One possible explanation is the presence of RIPK1-independent necroptosis in psoriasis." (PMID 32075957, 2020). "While the current findings support minimal diminished cytokine expression, the changes in disease activity were not statistically analyzed; therefore, the findings in this study may be insufficient to accurately assess the therapeutic potential of targeting RIPK1 in psoriasis." (PMID 41019071, 2025). "The heightened expression of necroptosis-associated molecules such as RIPK1 and RIPK3, along with the activation of necroptosis facilitated by the RIPK1/RIPK3 pathway, significantly contribute to the upregulation of IL-17, thereby inducing chronic inflammation in psoriasis." (PMID 39480805, 2024). "RIPK1 inhibitors are in phase IIa clinical trial for treating mild to moderate psoriasis, however further studies are needed to evaluate whether RIPK1 inhibitors have potential as new therapy for treating psoriasis." (PMID 37688617, 2023). "Thus, regulation of the early cell death checkpoint that safeguards the cytotoxic potential of RIPK1 is of clinical relevance, potentially offering new therapeutic opportunities for chronic inflammatory diseases, such as rheumatoid arthritis, psoriasis and septic shock." (PMID 36171264, 2022). "Further, the pharmacological inhibition of RIPK1 and RIPK3 through Nec-1s and NSA, respectively, confirmed the role of necroptosis in inflammatory cascades in both in vitro and in vivo psoriasis models." (PMID 36361505, 2022). "Among them, the first RIPK1 inhibitor GSK2982772 has entered clinical trials for the treatment of ulcerative colitis, psoriasis, rheumatoid arthritis, and other inflammatory diseases." (PMID 35805993, 2022). "Despite genetic evidence that the IAPs and RIPK1 can repress inflammatory skin lesions, studies into RIPK1 and RIPK3 function in the context of psoriasis are limited." (PMID 33924766, 2021). "Immunofluorescence of TUNEL and immunohistochemical labeling of active caspase-3, RIPK1, and MLKL suggest that necroptosis mainly occurs in the upper epidermis, which is similar to the results in psoriasis patients." (PMID 32075957, 2020). "Moreover, they have shown that the downregulation of RIPK1 increased its sensitivity to TNF-related apoptotic cell death ligands, which is critical in the pathology of psoriasis." (PMID 36361505, 2022). "Similarly, there was significant up-regulation of RIPK1 and RIPK3 in psoriasis tissues compared to normal samples." (PMID 32075957, 2020). "Other RIPK1 inhibitors have been developed by GlaxoSmithKline, among which GSK2982772 is currently in phase 2a clinical studies for psoriasis, rheumatoid arthritis, and ulcerative colitis and GSK3145095 has terminated the phase I clinical trials for solid tumors." (PMID 33050394, 2020). "Accordingly, some RIPK1 kinase inhibitors are now in phase I clinical trials for ALS and phase II clinical trials for psoriasis, rheumatoid arthritis, and ulcerative colitis, but to date no pharmacological inhibitor of RIPK1-mediated cell death is approved for regular clinical use." (PMID 33273695, 2021). "The expression of RIPK1 is elevated in psoriatic lesions compared with no lesion skin and atopic dermatitis, but downregulated RIPK1 enhances tumor necrosis factor-related apoptosis-inducing ligand (TRAIL) signaling in psoriasis." (PMID 36742336, 2023).
breast carcinoma (34 papers, 2015 to 2026). "For instance, high expression of RIPK1 was linked to metastasis in breast cancer and poor survival in glioblastoma, but was a good prognostic indicator in head and neck cancer." (PMID 38961535, 2024). "In head and neck squamous cell carcinoma and liver cancer, the low expression of RIPK1 is associated with poor prognosis, while in breast cancer (BC) and glioblastoma, the high expression of RIPK1 leads to poor prognosis." (PMID 36050939, 2022). "The results also showed that recent studies are increasingly focused on tumor regulation, with these keywords continuing until 2021, including membrane, breast cancer, protection, RIPK1, modulation, pseudokinase MLKL, deficiency, and cycle." (PMID 36204681, 2022). "Low expression of RIPK1 is linked to a bad prognosis in head and neck squamous cell carcinoma and liver cancer, whereas high expression of RIPK1 is linked to a poor prognosis in breast cancer (BC) and glioblastoma." (PMID 37663658, 2023). "In our study, RIPK1 inhibitors significantly blocked OpA-induced cell death in breast cancer cells, including TNBC, indicating that RIPK1 is involved in triggering the cell death pathway." (PMID 41596270, 2026). "The interaction between FASLG and FAS activates RIPK1, leading to necrosome formation that trigger necroptosis in tumor cells, potentially indicating breast cancer." (PMID 38460046, 2024). "Because RNA transcript levels do not always predict protein activity, it will be interesting to further explore the role of these ‘RIPK1 blockers’ in ER+ breast cancers." (PMID 32341449, 2020). "In the analysis for RFS, differential expression of ZNF611, ZNF304, RIPK1, DUSP8, TNFRSF21 and HRAS genes was associated with outcome for breast cancer patients who received radiotherapy." (PMID 30938061, 2019). "Conversely, RIPK1 levels are elevated in several other breast cancer subtypes." (PMID 41334873, 2025). "Our data clearly indicate that the DS variant-induced redox imbalance is an event upstream of the MLKL activation that was promoted by these molecules in luminal breast cancer cells, although the involvement of oxidized RIPK1 in this process remains unknown." (PMID 39062543, 2024). "Furthermore, for RIPK1/3 activation and necrosome complex formation, shikonin also provoked oxidative stress in glioma, gastric, nasopharyngeal, and breast cancer cells, which inhibits growth and metastasis of cancer cells through necroptosis induction." (PMID 36361505, 2022). "Phenytoin, a clinically used anticonvulsant, could inhibit RIPK1 activity in epilepsy and breast cancer." (PMID 34977874, 2021). "LCL161 sensitivity patterns were supported by mechanistic analyses of the drug targets and TNF-α signaling, indicating target engagement and a potential for response prediction by RIPK1 gene expression levels, consistent with previously published clinical data in breast cancer." (PMID 34496878, 2021). "However, we found RIPK1 was strikingly downregulated in TNBC compared with other breast carcinoma subtypes based on the analysis of the TCGA and GTEx datasets (p < 0.01)." (PMID 33980862, 2021). "However, the role of RIPK1 in breast cancer oncogenesis and development remains one of the major unsolved issues, which may lead to a better understanding of AQP1-related TNBC cell death escape." (PMID 33980862, 2021). "Two of these genes (RIPK1 and TNF) were recently reported as part of a three-gene signature that identifies breast cancer patients that benefit from the IAP inhibitor LCL161, administered in combination with paclitaxel." (PMID 40694850, 2025). "Data from breast cancer research indicates that the formation of RIPK1/RIPK3 necrosomes is essential for mediating ICD in cancer cells, while autophagic degradation of necrosomes results in ICD failure in breast cancer cells." (PMID 41334873, 2025).
breast carcinoma (continued). "Clinical studies also reveal that RIPK1 and MLKL mRNA expression levels exhibit a significant downward trend in breast cancer tissues, potentially increasing intrinsic resistance to lethal signals and enabling evasion of immune surveillance." (PMID 41334873, 2025). "In human breast cancer, it has been shown that necrosis can occur through finely tuned regulation of a series of pro-necrotic genes including MLKL, RIPK1, RIPK3, PGAM5, and DFNA520." (PMID 38773214, 2024). "Knockout of the RIPK1, RIPK3, or MLKL genes in breast cancer cells significantly reduces the oncogenic activity of these cells and sensitizes the breast cancer cells to radiation therapy." (PMID 35965497, 2022). "Zinc oxide nanoparticles (ZnO-NP) significantly induce necroptosis by the upregulation of RIPK1, RIPK3, and MLKL expression in human MCF-7 breast cancer cells." (PMID 36361505, 2022). "RIPK1, RIPK3, and MLKL have been found to promote tumorigenesis in several breast cancer cell lines, and the suppression of these factors can significantly weaken the tumorigenicity and sensitize therapeutic response to radiotherapy." (PMID 33665167, 2020). "A clinical study of breast cancer tissue specimens showed that compared to adjacent non-cancerous tissues, the mRNA and protein expression levels of tumor necrosis factor alpha (TNFα), RIPK1, RIPK3, and MLKL were significantly elevated in breast cancer tissues." (PMID 41346619, 2025). "When administered together with HMA (30 μM and 40 μM) for 24 h, NEC did not rescue HMA-induced cell death, thus suggesting that in HCT-116 cells RIPK1 is not involved in the cellular response to HMA, as already shown in breast cancer cells." (PMID 27816051, 2016).
Alzheimer disease (33 papers, 2018 to 2025). A progressive, neurodegenerative disease characterized by loss of function and death of nerve cells in several areas of the brain leading to loss of cognitive function such as memory and language. "The upregulated DAM genes and macrophage/microglia expression of Ripk1 in the authentic model of Krabbe disease strongly resemble those reported in Alzheimer disease associating with disturbed autophagosomal/lysosomal homeostasis." (PMID 34172992, 2021). "Targeting receptor‐interacting protein kinase 1 (RIPK1) has emerged as a promising therapeutic stratagem for neurodegenerative disorders, particularly Alzheimer's disease (AD)." (PMID 38923244, 2024). "Despite demonstrating promise in targeting RIPK1 for the treatment of Alzheimer’s disease, SAR443060, another orally bioavailable CNS penetrant investigational agent, was abandoned due to long-term toxicities." (PMID 38274328, 2024). "IKBKB can alleviate the neuron injury in Alzheimer’s Disease via regulating autophagy and RIPK1-Mediated necroptosis." (PMID 38020922, 2023). "Necroptosis, a programmed form of necrotic cell death carried out by receptor-interacting serine/threonine protein kinase 1 (RIPK1) and RIPK3, has been found to be implicated in the pathogenesis of Alzheimer’s disease (AD)." (PMID 37458952, 2023). "Recently, involvement of RIPK1 in the pathophysiology of Alzheimer’s disease (AD) has been reported; RIPK1 is highly expressed in the neurons and microglia in the postmortem brains of AD patients." (PMID 37853253, 2023). "We conclude that as reported in microglia in the APP/PS1 (amyloid precursor protein/presenilin 1) murine model of Alzheimer’s disease, upregulation of Ripk1 in both twitcher and SD mice, predominantly occurs in activated macrophage/microglia." (PMID 34172992, 2021). "The literature was searched on PubMed including the words PKR, MKK6, p38, MK2, RIPK1, and Alzheimer’s disease." (PMID 33808629, 2021). "Increased necroptosis has been reported in the postmortem brains of Alzheimer’s disease patients, i.e., an increase in the expression of RIPK1, RIPK3, MLKL, and P-MLKL." (PMID 34515928, 2021). "Evidences emerged that RIPK1 activation increased in the microglia of brains in Alzheimer’s disease." (PMID 30042663, 2018). "Moreover, the findings demonstrate that [11C]CNY‐10 can be used for research on the diagnosis and pathological mechanisms of Alzheimer's disease (AD) and potentially other RIPK1‐related diseases." (PMID 38923244, 2024). "Recently, the involvement of RIPK1 in the pathophysiology of Alzheimer’s disease (AD) has been reported; RIPK1 is involved in microglia’s phenotypic transition to their dysfunctional states, and it is highly expressed in the neurons and microglia in the postmortem brains in AD patients." (PMID 37853253, 2023). "Receptor interacting protein 1 (RIPK1) is a critical mediator of the programmed necrosis pathway that is involved in stroke, myocardial infarction, fatal systemic inflammatory response syndrome, Alzheimer’s disease, and malignancy." (PMID 36249746, 2022). "Since RIPK1 activation and necroptosis have been genetically and mechanistically linked with human neurodegenerative diseases such as MS, ALS and Alzheimer’s disease (AD), keen interests have been sparkled on developing CNS-penetrant new RIPK1 inhibitors as drug candidates to treat CNS diseases." (PMID 35365618, 2022). "RIPK1 was highly expressed in microglia in Alzheimer’s disease (AD)." (PMID 36249746, 2022). "Furthermore, inhibiting RIPK1 activation alleviated neuroinflammation and cognitive impairments during Alzheimer’s disease, and didn’t show obvious toxic effect." (PMID 30042663, 2018). "Recent studies found RIPK1 modulated the neuroinflammation in Alzheimer’s disease." (PMID 30042663, 2018). "The keywords include "necroptosis", "RIPK1", "RIPK3", "MLKL", "pMLKL", "necroptosis inhibitors", "Alzheimer’s disease", and "neurodegeneration"." (PMID 41042431, 2025).
Alzheimer disease (continued). "In the Alzheimer’s disease model, DHA may block necroptosis of THP-1 cells triggered by Aβ via the RIPK1/RIPK3 signaling pathway." (PMID 36895263, 2023). "Necroptosis, which is mediated by receptor-interacting protein kinase 1 (RIPK1 or RIP1), RIPK3 (or RIP3), and the pseudokinase MLKL, promotes necrotic cell death and neuroinflammation in Alzheimer’s disease (AD), amyotrophic lateral sclerosis (ALS), multiple sclerosis (MS), and PD." (PMID 38041169, 2023). "Currently, numerous RIPK1 inhibitors are in different phases of clinical trials for a spectrum of human inflammatory diseases, ranging from rheumatoid arthritis, cutaneous lupus erythematosus, ulcerative colitis, SARS-CoV-2 infection, to Alzheimer’s disease and ALS (ClinicalTrials.gov)." (PMID 39062098, 2024). "Increased RIPK1 expression in the human brains with TBI might be crucial not only as a mechanism that promotes neural death and neuroinflammation in the acute phase, but also sensitizes a variety of chronic traumatic encephalopathy, including Alzheimer’s disease and Parkinson’s disease." (PMID 38374093, 2024).
pancreatic cancer (30 papers, 2017 to 2025). "In a pancreatic cancer model, administration of RIPK1 inhibitors has been shown to reprogram tumor-associated macrophages from a tolerogenic to an immunogenic state." (PMID 33567618, 2021). "For instance, RIPK1 is heavily expressed by tumor-associated macrophages (TAMs) in pancreatic cancer wherein RIPK1 facilitates TAMs-driven immunosuppression (possibly via its scaffolding functions)." (PMID 32752206, 2020). "In certain malignancies, such as glioblastoma, lung cancer, and pancreatic cancer, RIPK1 expression seems to be augmented." (PMID 40007541, 2025). "In pancreatic cancer, its overexpression accelerates tumor progression by inhibiting necroptosis through the RIPK1/RIPK3/MLKL signaling cascade." (PMID 41180485, 2025). "For example, GSK31450595, a highly specific RIPK1 kinase inhibitor, is currently undergoing Phase I clinical trials for pancreatic cancer and other solid tumors." (PMID 40301325, 2025). "As a result of increasing mitochondrial Ca2+ levels, which produce superoxide and, subsequently, activate RIPK1, pancreatic cancer cells undergo necroptosis in response to agonists of the APN receptor (AdipoRon)." (PMID 37893166, 2023). "At the same time, the upregulation of RIPK3 or RIPK1 is involved in the occurrence and progression of glioma, pulmonary carcinoma, and pancreatic cancer." (PMID 37580654, 2023). "The aurora kinase inhibitor, CCT137690, triggered the necroptosis of pancreatic cancer cells by RIPK1, RIPK3, and MLKL, and hindered the growth of in situ pancreatic tumors in mice." (PMID 36981005, 2023). "And phase I/II trials (NCT03681951) about GSK3145095, one RIPK1 inhibitor, have been aborted in pancreatic cancer and headed back to the company’s research and development." (PMID 35725836, 2022). "The aurora kinase inhibitor CCT137690 triggers necroptosis in pancreatic cancer cells through RIPK1, RIPK3, and MLKL and thus suppresses tumor growth." (PMID 35662734, 2022). "A mouse model of pancreatic cancer showed that knocking out RIPK3 or RIPK1 inhibited oncogenic progression." (PMID 35725836, 2022). "RIPK3/RIPK1 regulation of CXCL1 in pancreatic cancer restricts infiltration of highly immunogenic T or B cells to promote tumor migration and invasion." (PMID 35965497, 2022). "To date, only one compound that targets RIPK1 has been characterized for treatment of pancreatic cancer and it is in phases I/II." (PMID 33567618, 2021). "This point is particularly poignant considering withdrawals of certain RIPK1 inhibitor drugs from phase I (pancreatic cancer) and II (chronic inflammatory diseases) clinical trials due to lack of efficacy." (PMID 34071602, 2021). "Subsequent research proposed that RIPK1 kinase might facilitate macrophage-mediated adaptive immune tolerance in pancreatic cancer." (PMID 40007541, 2025). "Notably, our recent study has confirmed that 6-ME can induce mitochondrial dysfunction and ROS/RIPK1-dependent pyroptosis that hinder pancreatic cancer progression." (PMID 37214469, 2023). "In addition, another anti-diabetic drug, the Vanadium compound, triggered various cell death in pancreatic cancer by inhibiting the cell cycle, increasing ROS, and upregulating RIPK1 and RIPK3 in a dose-dependent manner." (PMID 37893166, 2023). "Using a RIPK3 rescue model in a RIPK3-deficient pancreatic cancer cell line which normally cannot undergo necroptosis, we demonstrate that the evolutionary conserved dimethylated arginine residue R486 is important for RIPK3-mediated feedback control on RIPK1 autophosphorylation." (PMID 36658119, 2023). "Moreover, some chemokines released from necroptotic cells can in fact support pro-cancerous processes, e.g., RIPK3/RIPK1-driven CXCL1 in pancreatic cancer can facilitate tumor progression (via TAMs and MDSCs) by restricting infiltration of highly immunogenic T or B cells." (PMID 32752206, 2020).
pancreatic cancer (continued). "In pancreatic cancer, CHMP4C facilitates progression by inhibiting necroptosis via the RIPK1/RIPK3/MLKL pathway, thereby emphasizing its role in cell survival and proliferation." (PMID 40893939, 2025). "Despite IMB5036′s ability to partially activate apoptosis and pyroptosis, its primary mode of action is necroptosis, initiated by the upregulation of RIPK1, RIPK3, and largely MLKL in pancreatic cancer cells." (PMID 37893166, 2023). "Its inhibitor, CCT137690, induced the necroptosis of PC cells via RIPK1, RIPK3, and MLKL, and impeded the growth of in situ pancreatic tumors in mice." (PMID 35740953, 2022). "In contrast, it is reported that RIPK1 and RIPK3 are overexpressed in pancreatic cancer tissues, and downregulation of RIPK1 or deletion of RIPK3 in vivo inhibited tumor progression via enhancing immune cell infiltration." (PMID 35756487, 2022). "RIPK1 and RIPK3 can induce necroptosis to drive pancreatic cancer progression." (PMID 37016317, 2023). "In fact, these observations instigated the testing of pharmacological inhibitors of RIPK1 in pancreatic cancer patients (with or without combination with anti-PD1 immunotherapy) with the aim to ameliorate the immunosuppressive tumor milieu." (PMID 32752206, 2020).